LATS2 (large tumor suppressor kinase 2)
Diseases named in the same sentence as LATS2 in open-access papers (continued):
Sharing a sentence is not in itself a finding about the gene and the disease.
mesothelioma (24 papers, 2011 to 2024). A usually malignant and aggressive neoplasm of the mesothelium which is often associated with exposure to asbestos. "LATS2 mutation or inactivation is a positive regulator of mesothelioma proliferation via constitutively activating YAP and Hippo signaling pathways." (PMID 36237331, 2022). "Mutations of Hippo pathway components, such as LATS1 and LATS2, have been observed in many mesothelioma specimens with aberrant YAP activation." (PMID 34226685, 2021). "In two mesothelioma cell lines [MSTO-211H (LATS2 mutation) and H2373 (NF2 mutation)] and RPE1 cells, survival was significantly reduced at 72 hours after YAP/TAZ siRNA transfection." (PMID 32277165, 2020). "For example, mutation in Lats2, which is one of the components of the Hippo pathway, responded to 40% of mesothelioma cases." (PMID 28837560, 2017). "More recently, studies of YAP modulation by the LIM‐domain protein AJUBA, a binding partner of LATS2, found that mesothelioma cells frequently showed loss of AJUBA expression, which contributes to aberrant YAP activation." (PMID 28470935, 2017). "Disruption of the YAP/TAZ–TEAD interaction by IAG933 and YTP-75 was demonstrated by coimmunoprecipitation following incubation of the Hippo-altered mesothelioma cell line MSTO-211H (LATS1/LATS2 loss of function) with IAG933 or YTP-75, an IAG933 analog with a cellular potency within a similar range." (PMID 38565920, 2024). "In addition, YAP1 is negatively regulated by large tumor suppressor kinases (LATS1 and LATS2), which are commonly deleted in mesothelioma; in contrast, forced expression of LATS2 inactivates YAP1 and causes a reduction in cell growth." (PMID 29342862, 2018). "Among tumor lines with Hippo pathway mutations analyzed by us, one mesothelioma, H2052, with both LATS2 and NF2 mutations, was found to be resistant to XAV939 despite its striking sensitivity to dnTEAD4 inhibition of TEAD-mediated transcription and proliferation." (PMID 27144834, 2016). "This is exemplified by large tumor suppressor kinase 2 (LATS2) in mesothelioma and LATS1/2 in pancreatic cancer." (PMID 37628858, 2023). "Recent whole-genome analysis has revealed that mesothelioma is characterized by a high frequency of mutations in a set of genes involved in the Hippo pathway, such as NF2 and LATS2." (PMID 37165917, 2023). "Among the hyper-altered cancer types, mesotheliomas and papillary renal cell carcinomas were the most significant, and this finding was likely related to a high frequency of NF2, LATS2, and SAV1 mutations." (PMID 31959902, 2020). "To validate our whole-genome screens, we used CRISPR/Cas9 mutagenesis with two independent sgRNAs to mutate NF1, SOCS3, and VGLL4 in H226 and H2052 cells, as well as a third mesothelioma cell line, MSTO-211H, which harbors inactivating mutations in both LATS1 and LATS2." (PMID 39103676, 2024). "In recent studies, NF2 and LATS2, both belonging to the hippo pathway, were identified as key drivers for non-asbestos-related tumorigenesis for mesothelioma, although both also play a role in patients with mesothelioma who were exposed to asbestos." (PMID 35205798, 2022). "Mutations in known mesothelioma-related genes NF2, CDKN2A, LATS2, amongst others, were identified." (PMID 25798586, 2015).
mesothelioma (continued). "The first subgroup explored novel tumor suppressor gene(s) in mesothelioma cells and found that the serine/threonine-protein kinase (LATS2) gene is inactivated in approximately one-third of mesothelioma cell lines and is a candidate for a novel tumor suppressor in MM." (PMID 22007251, 2011). "In mesothelioma, due to the NF2 or LATS2 loss, Hippo signaling becomes dysregulated, although the observation of frequent subclonal NF2 mutations detected in clinical samples suggests that it may occur later in mesothelioma development." (PMID 36221913, 2022). "Furthermore, co-inactivation of LATS2 and NF2 in mesothelioma cell lines triggers the loss of cell–cell contact inhibition, dysregulation of Hippo and mammalian target of rapamycin (mTOR) signalling, and correlates with higher sensitivity to inhibitors of the PI3K–AKT–mTOR pathway." (PMID 34226685, 2021). "Thus the expression of the other genes commonly deleted in human mesothelioma, NF2, BAP1 and LATS2 was investigated." (PMID 26680231, 2015). "We found RASSF7 amplification in 39 mesotheliomas, NF2 mutations in 24, LATS2 mutations in 6 and LATS1 in 2, so that non-overlapping lesions in Hippo pathways were present in 52/121 mesotheliomas (43%) and a further 9 mesothelioma had more than one lesion (total 50%)." (PMID 34580349, 2021).
colorectal cancer (23 papers, 2011 to 2025). A primary or metastatic malignant neoplasm that affects the colon or rectum. "For instance, overexpression of miR-372 promotes the proliferation and migration of colorectal cancer cells by inhibiting the tumor suppressor gene LATS2." (PMID 37445863, 2023). "For example, the Hippo signaling pathway kinase LATS2 has been reported to disrupt BCL9-β-catenin interaction in a kinase-independent function in colorectal cancer cells." (PMID 34545187, 2021). "Subsequently, they validated the upregulation of 5′tiRNA-His-GTG in tumor tissues using RT-qPCR in 25 paired tissue samples and further found that this tsRNA enhanced colorectal cancer cell proliferation and anti-apoptotic capacity by targeting LATS2 and inhibiting the Hippo signaling pathway." (PMID 40649749, 2025). "In addition, the 5′ tiRNA-His-GTG was shown to promote colorectal cancer progression by targeting LATS2 expression." (PMID 36388094, 2022). "RASAL2 can also promote the progression of colorectal cancer through the LATS2 / YAP axis." (PMID 34430085, 2021). "Moreover, our results indicate that miR-31-5p is not only related to tumors but also regulates colorectal cancer cell sensitivity to the chemo drug by targeting LATS2." (PMID 31623173, 2019). "In colorectal cancer, RASAL2 interacts with Hippo regulator LATS2, preventing YAP from degradative ubiquitination and thereby enabling its oncogenic function as a nuclear transcription co-factor." (PMID 39890967, 2025). "Our findings highlight a regulatory network involving KLF15, LINC00689, PTBP1, LATS2, and the YAP1/β-catenin pathway in colorectal cancer, shedding light on potential therapeutic targets for colorectal cancer therapy." (PMID 38273088, 2024). "Another study also showed that miR-103a-3p knockdown suppressed HIF1A expression by targeting the core molecules LATS2 and SAV1 of the Hippo/YAP1 pathway, contributing to reduced proliferation, invasion, migration, glycolysis and angiogenesis in colorectal cancer." (PMID 35094292, 2022).
gastric cancer (22 papers, 2011 to 2025). A primary or metastatic malignant neoplasm involving the stomach. "While antral stem cells expressing Lgr5, Mist1 or Sox2 may be among the gastric cancer origin cells in the setting of Apc loss, Lgr5+ cells have been implicated in more invasive types of gastric cancer, characterized by the simultaneous loss of Pten and Smad4, or by the loss of Lats1 and Lats2." (PMID 30384487, 2018). "For instance, a series of biochemical experiments in gastric cancer cells revealed that the C terminus of WBP2 is responsible for binding to the C terminal kinase domain of LATS2." (PMID 34831354, 2021). "The inhibition of miR-372 biogenesis was confirmed in gastric cancer cells overexpressing miR-372 and a specific inhibition of proliferation through de-repression of the tumor suppressor LATS2 protein, a miR-372 target, was observed." (PMID 29374231, 2018). "LATS2, which is an important tumor suppressor, plays an important role in inhibiting cell proliferation in gastric cancers." (PMID 24552534, 2014). "LncRNA CCAT2 promotes gastric cancer proliferation and invasion through regulating the E-cadherin and LATS2.And LINC00240 promotes GC tumorigenesis via a LINC00240/miR-124-3p/DNMT3B axis as an oncogene, so it may be a potential diagnostic biomarker for GC." (PMID 34422902, 2021). "Interestingly, knockdown of EZH2 also resulted in increased LATS2 expression in gastric cancer cells." (PMID 32157157, 2020). "Previous studies showed that CCAT2 overexpression promoted LATS2 expression in gastric cancer cell." (PMID 29502343, 2018). "Similarly, lncRNA LINC00152 and lncRNA CCAT2 interact with EZH2 and guides it to suppress gene expression of p15 and p21 and E-cadherin and LATS2 in gastric cancer cells to promote cancer proliferation in vitro and in vivo." (PMID 28561778, 2017). "Additionally, gastric cancer progression is associated with the lncRNA LINC00673 through the interaction with LSD1 and EZH2, leading to inhibition of KLF2 and LATS2 expression to exert oncogenic functions in vitro and in vivo." (PMID 28561778, 2017). "LSD1 recruited by Lnc00673l binds to the promoter regions of LATS2 (large tumor suppressor kinase 2) and KLF2 (Krüppel-like factor 2) and decreases methylation levels, thereby inducing growth arrest and decreased invasion of gastric cancer cells." (PMID 40028036, 2025). "In the context of lung and gastric cancers, WBP2 has been shown to negatively regulate LATS1 and LATS2 kinase activity through WW domain-dependent and WW domain-independent mechanisms, respectively." (PMID 34831354, 2021). "On the other hand, WBP2 may bind directly to LATS2 to bring about inhibition of LATS2 phosphorylation and YAP/TEAD activity in gastric cancer cells, as reported by our laboratory." (PMID 34831354, 2021). "Many studies have found that large tumor suppressor kinase 1 (LATS1) and LATS2 play important roles in many diseases, but studies have been rare on the relationship between these genes and non-cardia gastric cancer (GC)." (PMID 32423384, 2020).
hepatocellular carcinoma (17 papers, 2011 to 2025). A malignant tumor that arises from hepatocytes. "JCAD can interact with large tumor suppressor kinase 2 (LATS2), thereby inhibiting the ability of LATS2 to phosphorylate yes-associated protein (YAP) in hepatoma cells in vitro." (PMID 41374934, 2025). "Published research studies on LATS2 have been mainly performed on glioma, osteosarcoma, and hepatocellular carcinoma." (PMID 36118851, 2022). "For instance, miR-650 directly targets and inhibits the expression of LATS2 to promote the metastasis and epithelial-mesenchymal transition of hepatocellular carcinoma cells." (PMID 34131399, 2021). "Simultaneously, miR-103 fosters metastasis and EMT by targeting LATS2 in hepatocellular carcinoma." (PMID 36118851, 2022). "In addition, a recent study showed that miR-103a-3p inhibits the Hippo pathway and activates YAP by directly targeting LATS2, ultimately promoting hepatoma cell metastasis and EMT." (PMID 33218358, 2020). "A recent study reported that miR-103a-3p promoted the activation of Hippo pathway via targeting large tumor suppressor kinase 2 (LAST2), ultimately promoting hepatoma cell metastasis and EMT." (PMID 35094292, 2022). "Up-regulation of JCAD inhibits the ability of LATS2 to phosphorylate YAP, thus elevating CCND1 and Gli2 expression to promote hepatoma cell proliferation." (PMID 32493490, 2020). "In this scenario, JCAD binds to the domain of LATS2 kinase and inhibits the ability of LATS2 to phosphorylate YAP, which in turn activating YAP to promote hepatoma cell proliferation." (PMID 30176928, 2018). "For instance, ectopic expression of Dnd1 promotes LATS2 mRNA decay through binding to the LATS2 3’-UTR, thus promoting YAP phosphorylation and inhibiting Epithel-to-Mesenchymal Transformation (EMT) in hepatocellular carcinoma (HCC)." (PMID 39890775, 2025). "Although LATS1 and LATS2 kinases, core components of the mammalian Hippo pathway, have been shown to exert tumor suppressive activities, here we report a pro-survival role of LATS1 but not LATS2 in hepatocellular carcinoma (HCC) cells." (PMID 31848340, 2019).
ovarian cancer (17 papers, 2015 to 2026). A primary or metastatic malignant neoplasm involving the ovary. "In this study, we proved through of evidences that miR-363 decrease and subsequent increase of LATS2 are associated with the acquisition of TX-resistance in ovarian cancer." (PMID 30046387, 2018). "MiR-363, together with LATS2, might be a potential diagnostic marker to predict patient prognosis and responsiveness to TX in ovarian cancer while targeting miR-363 may overcome TX resistance." (PMID 30046387, 2018). "Next, we determined the expression of SIPR1, YAP, LATS1, and LATS2 in human ovarian cancer tissues using immunohistochemistry." (PMID 37828220, 2023). "Here, we analyzed LATS1 and LATS2 gene expression in publicly available ovarian cancer transcriptomic data sets." (PMID 31586262, 2019). "To evaluate the possible relationship between the miR-363-LATS2 axis and development of ovarian cancer chemoresistance, we examined the expression level of LATS2 in surgical specimens from 10 human ovarian cancer tissues." (PMID 30046387, 2018). "MiR-25 also promotes apoptosis resistance in cholangiocarcinoma by targeting TRAL death receptor-4, as well as ovarian cancer proliferation and motility by targeting LATS2." (PMID 26460549, 2015). "Finally, miR-25 has been reported to stimulate growth and invasion of ovarian cancer cells by targeting key tumor-suppressors, including LATS2 and BIM, while miR-25 overexpression in ovarian cancer patients has been associated with adverse disease outcome." (PMID 37024879, 2023). "Pverexpression of YAP1 and under expression of LATS2 in ovary cancer also had poor prognosis." (PMID 36552980, 2022). "Furthermore, LATS2 was a tumor suppression gene in ovarian cancer and decreased LATS2 led to upregulation of PD-L1, which subsequently promoted T cell apoptosis and suppressed NK cell function." (PMID 34699318, 2021). "Interestingly, TCGA RNASeqV2 data for serous high-grade ovarian cancer showed that both LATS1 and LATS2 expressions were associated with a higher risk for poorer survival (HR = 1.14 for LATS1 and HR = 1.08 for LATS2) for this more homogenous group of patients." (PMID 31586262, 2019). "Interestingly LATS1 and LATS2 proteins were higher or at least comparably expressed in ovarian cancer cell lines compared to “normal” HOSE and FT cell lines, but in no case LATS protein expression was decreased relative to the “normal” cell lines." (PMID 31586262, 2019). "QRT-PCR indicated that miR-363 was upregulated in KF-TX cells, and introduction of miR-363 into sensitive ovarian cancer cells confers TX-resistance and significantly inhibited the expression of the Hippo member, LATS2, as indicated by viability, clonogenic assay and expression analysis." (PMID 30046387, 2018). "Furthermore, we validated the role of LATS2 in TX-response by sh-based silencing, which also confers TX-resistance to the ovarian cancer cells." (PMID 30046387, 2018). "In addition, endogenous LATS2 was found to be downregulated in KF-TX cells compared with the parental KF cells, suggesting that LATS2 is a putative target for miR-363 in the cellular set of ovarian cancer used here." (PMID 30046387, 2018). "In addition, our data showed that, like siRNA-based depletion, miR-363 overexpression reduces LATS2 expression which in turn reduce the cellular growth rate, and subsequently reduced response to TX in ovarian cancer cells." (PMID 30046387, 2018). "LATS2 is mapped to chromosome 13q11-12 and was reported to be positively expressed in serous cystadenomas, with the expression levels gradually decreased in borderline cystadenomas and carcinomas of the ovary." (PMID 30046387, 2018). "MiR-181b was also reported to promote ovarian cancer cell growth and invasion by targeting LATS2." (PMID 29145896, 2017). "MiR25 is overexpressed in ovarian cancer tissues by targeting LATS2." (PMID 26262875, 2015).
ovarian cancer (continued). "Several interesting findings emerged from this study: Firstly, the analysis of 15 databases indicated that neither LATS1 nor LATS2 expression was associated with favorable survival in ovarian cancer and that LATS2 may even have a negative role for survival." (PMID 31586262, 2019). "Collectively, neither LATS1 nor LATS2 expression was associated with favorable survival in ovarian cancer and LATS2 expression may even have a negative effect on survival." (PMID 31586262, 2019). "Taken together, our study reveals the involvement of miR-363 in chemoresistance by targeting LATS2 in ovarian cancers, raising the possibility that combination therapy with a miR-363 inhibitor and TX may increase TX efficacy and reduce the chance of TX-resistance." (PMID 30046387, 2018). "Our results support the idea that LATS2 expression could be reduced by an alternative mechanism, rather than promoter hypermethylation, which is the upregulation of miR-363, leading to the acquisition of TX resistance in ovarian cancer cells." (PMID 30046387, 2018). "Give that poor survival of ovarian cancer is associated with chemoresistence, together with our findings, we can speculate that chemoresistance established by downregulation of LATS2 may explain the relation of miR-363upregulation with poor survival of ovarian cancer, albeit in part." (PMID 30046387, 2018). "To further verify the role of LATS1/2 in ovarian cancer cell senescence, we silenced LATS1 and LATS2 in S1PR1 knockout ovarian cancer cells." (PMID 37828220, 2023). "The lncRNA ATB binds to EZH2 and downregulates the expression of DAB2IP, CDH1, LATS2, FOXC1 and CDX1, thus facilitating the progression of ovarian cancer." (PMID 34890108, 2022). "Large tumor suppressor kinase 2 (LAST2) was reported to inhibit the proliferation and invasion as well as dictate senescence in ovarian cancer." (PMID 35004274, 2021). "A recent study revealed the novel mechanism that downregulation of LATS2 resulted in increased YAP1 translocation and up-regulated PD-L1 expression, finally leading to immune suppression in ovarian cancer." (PMID 34699318, 2021). "Additionally, it controls epithelial-mesenchymal transition to suppress proliferation and metastasis in ovarian cancer and hampers malignant transformation in NSCLC via the miR-141-3p/LatS2 axis and the miR-1278/SOCS6 axis." (PMID 39866239, 2025). "In addition, LATS2 interacted with YAP1 and restricted nuclear translocation of YAP1, which enhances transcription activity of PD-L1 and leads to immune escape in ovarian cancer." (PMID 35620733, 2022). "They neither support the putative function of LATS proteins as tumor suppressors nor are they consistent with the previous study of ovarian cancer patients, where elevated LATS1 and LATS2 expression was associated with better outcome in serous ovarian cancer patients." (PMID 31586262, 2019). "Also, expression of LATS1 and LATS2 is not necessarily interdependent, meaning that high LATS1 expression does not necessarily mean high LATS2 expression in ovarian cancer cell lines." (PMID 31586262, 2019).